INS (insulin)
Diseases named in the same sentence as INS in open-access papers (continued):
Sharing a sentence is not in itself a finding about the gene and the disease.
metabolic syndrome (continued). "The present study suggests that metformin decreased average glucose concentrations and insulin dose requirement, as well as lowered metabolic syndrome prevalence more than with insulin therapy alone after 1 year of treatment." (PMID 29338714, 2018). "The total use of weight, BP, blood glucose, CVD, and metabolic syndrome menus tended to increase, whereas the use of diseases, insulin, medication, and allergy menus tended to decline." (PMID 29631989, 2018). "In metabolic syndrome, sequestration of plasma glucose is impaired through typical insulin signaling, making AMPK-mediated signaling of particular interest as an alternate route for cellular glucose entry." (PMID 29049981, 2018). "Insulin and leptin resistance are known to play a role in metabolic syndromes and nonalcoholic fatty liver disease (NAFLD)." (PMID 30055626, 2018). "In brief, High-fat/high-glucose fed rats showed an increased body weight, abdominal circumference and fat deposition, combined with oxidative stress, raised fasting levels of glucose and insulin in plasma, dyslipidemia and mechanical allodynia." (PMID 30322196, 2018). "It is also possible that the composition of FAs in obese people with metabolic syndrome can induce changes in the fluidity of microsomal membranes, impairing ER function and thus also insulin secretion." (PMID 29921789, 2018). "The metabolic syndrome is accompanied by impaired glucose tolerance, insulin resistance in peripheral tissues, and raised fasting and postprandial glucose and insulin levels." (PMID 30301205, 2018). "Algae supplementation decreased weight and improved insulin sensitivity in metabolic syndrome animals." (PMID 29611042, 2018). "In these mice, pNaKtide not only significantly improved atherosclerosis, but also ameliorated steatohepatitis, dyslipidemia, and insulin sensitivity." (PMID 30200235, 2018). "Agonists of PPARα and PPARβ/δ have been used to treat dyslipidemia by increasing oxidative capacity in muscle fibers and improving insulin sensitivity." (PMID 30037087, 2018). "GC-based treatments are typically associated with glucose and lipid disturbances (i.e., glucose intolerance, reduction in insulin sensitivity, dyslipidemias of varied degrees, and hyperinsulinemia), which are well reproducible in both rodents and in humans." (PMID 30532777, 2018). "The ‘Metabolic-Syndrome’ Profile was positively loaded by the waist circumference, hypertension, and serum concentration of triglycerides, insulin, and glucose and was negatively loaded by the serum HDL-C concentration." (PMID 30572623, 2018). "LPA was inversely associated with all-cause mortality risk and associated favorably with some cardiometabolic risk factors including waist circumference, triglyceride levels, insulin, and presence of metabolic syndrome." (PMID 29986718, 2018). "The adiponectin-T2D association remained unchanged after adjusting for inflammation and dyslipidemia markers, but substantially attenuated with adjustment for insulin sensitivity and/or glycaemia markers." (PMID 29321603, 2018). "The total number of mPHR users was 18,265 (patients: n=16,729, 91.59%) with 3620 users having entered weight, followed by BP (n=1625), blood glucose (n=1374), CVD (n=764), metabolic syndrome (n=685), medication (n=252), insulin (n=72), and allergy (n=61)." (PMID 29631989, 2018). "With respect to the improved metabolic complications, it is well known that exercise training improves insulin and leptin resistance in conjunction with dyslipidemia by promoting glucose and fatty acid metabolism as well as enhanced mitochondrial biogenesis." (PMID 30343561, 2018). "This retrospective study suggests that metformin decreased glucose concentrations, lowered metabolic syndrome prevalence, as well as insulin dose requirement more than insulin therapy alone after 1 year of treatment." (PMID 29338714, 2018).
metabolic syndrome (continued). "The patients in the metformin-insulin and insulin alone groups were divided into subgroups as metabolic syndrome and control non-metabolic syndrome." (PMID 29338714, 2018). "In human participants, transfer of faecal microbiota from lean donors to recipients with the metabolic syndrome increased insulin sensitivity." (PMID 29502266, 2018). "The tables show a comparison between groups divided by median of selected insulin sensitivity and resistance indices for number of metabolic syndrome criteria." (PMID 30151057, 2018). "Fenofibrate treatment in patients with metabolic syndrome improves lipid profiles and increases insulin sensitivity." (PMID 29747466, 2018). "A key metabolic syndrome indicator is glucose intolerance, which is a measure of baseline glucose, baseline insulin, and the ability to respond to an exogenous glucose load with adequate insulin production." (PMID 30619467, 2018). "Metabolic syndrome refers to a cluster of abnormalities including impaired glucose metabolism, insulin sensitivity, obesity, and dyslipidemia." (PMID 30400826, 2018). "As hepatic manifestation of the metabolic syndrome, the development of NASH is associated with an impaired insulin metabolism." (PMID 30538805, 2018). "Patients with T2DM or MetS share common characteristics of raised blood sugar, decreased insulin sensitivity, obesity, dyslipidemia, and hypertension, which often appear simultaneously rather than alone." (PMID 29541142, 2018). "The study also revealed an improvement in mitochondrial fatty acid oxidation, insulin sensitivity, dyslipidemia, and aortic streaking in their model." (PMID 30200235, 2018). "Defects in insulin release, typical of T1DM and the animal model used, imbalance the release of glucagon, corticosteroids, and catecholamines and predispose to dyslipidemia and diabetic ketoacidosis." (PMID 30517288, 2018). "There is a strong linear increase in fasting insulin levels with an increase in the number of metabolic syndrome." (PMID 29724734, 2018). "Participants with the metabolic syndrome were more often men, were slightly older, had lower insulin sensitivity, and worse LGI, had higher prevalence of CVD, were more likely to use medication, and reported lower physical activity." (PMID 30132263, 2018). "Hypertension in the metabolic syndrome has been suggested to be related to preserved RPT sodium bicarbonate cotransporter sensitivity to insulin." (PMID 29642240, 2018). "The positive associations between increasing IFN-γ or TNF-α and insulin, as well as TNF-α with cholesterol, in this study support a similar role of inflammation and elevated cytokines in metabolic syndrome in dolphins." (PMID 29304133, 2018). "Acanthosis nigricans in overweight and obese children and adolescents isassociated with elevation of body fat, blood pressure, insulin andhomeostasis model assessment index, indicating that it is a clinical markerassociated with the metabolic syndrome." (PMID 30365811, 2018). "In conclusion, the present study suggests that the breeding sow undergoes metabolic syndrome including insulin insensitivity and low-grade inflammation during perinatal period, especially in early lactation." (PMID 30197635, 2018). "Metabolic syndrome with IR is a common adverse event associated with SSRI treatment which indicates a link between the serotonin and insulin system." (PMID 30123264, 2018). "In the current study, the breeding sows were found to suffer from symptoms of metabolic syndrome including low-grade inflammation during perinatal period and reduced insulin sensitivity in early lactation." (PMID 30197635, 2018). "One prominent PPARβ/δ-selective agonist is seladelpar (MBX-8025), which is currently in clinical phase 2/3 for primary biliary cirrhosis, and has previously been shown to improve the insulin sensitivity and dyslipidemia in overweight subjects." (PMID 29747466, 2018).
metabolic syndrome (continued). "Metformin has been shown to increase insulin sensitivity and reduce metabolic syndrome incidence in people with prediabetes." (PMID 29338714, 2018). "It would have been of great interest to see how well the insulin clamp predicts the metabolic syndrome in comparison to the other 21 insulin resistance indices that were evaluated." (PMID 30151057, 2018). "Plasma SHBG levels were negatively correlated with metabolic syndrome factors (BMI, waist circumference, and TG) and diabetic parameters (insulin and HOMA-IR)." (PMID 30057912, 2018). "It is known to improve insulin sensitivity, glycaemic control, hypertension, dyslipidemia, and microalbuminuria acting on PPAR-γ." (PMID 29744368, 2018). "Another study showing the deleterious effect of a high fructose diet was made in Rhesus monkeys that received a daily beverage containing 75 g of fructose for 12 months; those monkeys developed an increase in body fat, insulin resistance, and dyslipidemia." (PMID 30416829, 2018). "The present study suggests that metformin decreased glucose concentrations, lowered metabolic syndrome prevalence, as well as insulin dose requirement, more than insulin alone." (PMID 29338714, 2018). "Metabolic syndrome percentage was decreased in the metformin-insulin group (44.8 vs. 37.9%, p = 0.008) whereas it increased in the insulin alone group (41.4 vs. 44.8%, p = 0.035)." (PMID 29338714, 2018). "Fibroblast growth factor 21 (FGF21) emerges as an insulin-mimetic hormone that regulates systemic energy balance and has beneficial effects on body weight, insulin sensitivity, dyslipidemia, and pancreatic β-cell growth." (PMID 28677104, 2018). "The synergetic attenuation of pancreatic redox imbalance, dyslipidemia; modulation of glucose and insulin homeostasis; as well as improved pancreatic β-cell distribution and function suggests possible antidiabetic mechanisms." (PMID 29449808, 2018). "It is possible that elevated uric acid worse insulin sensitivity and metabolic syndrome and vice versa." (PMID 30563493, 2018). "The highest insulin quintile was almost 200 times more likely to be classified with the metabolic syndrome than participants in the lowest quintile." (PMID 29724734, 2018). "Steatosis was induced by cell culture media which consisted of elevated levels of free fatty acids, monosaccharides and insulin to reflect the in vivo environment the liver is exposed to in patients with the metabolic syndrome." (PMID 30250238, 2018). "We suggest that metformin likely improved glycemic control more than with insulin alone and this also contributed to metabolic syndrome reductions." (PMID 29338714, 2018). "We found that a combination of free fatty acids, monosaccharides and insulin (‘metabolic syndrome’) together resulted in a >2-fold increase in FASN mRNA expression (p < 0.05)." (PMID 30250238, 2018). "The best example of compromised metabolic flexibility in metabolic syndrome is a deteriorated insulin-mediated substrate switching." (PMID 29697773, 2018). "In this paper, our purposes were to evaluate the metabolic activity on dyslipidemia and dysglycemia, insulin signaling in liver and adipose tissue, and toxicology of the title compound." (PMID 30026756, 2018). "Moxonidine is a centrally acting sympatholytic drug with known beneficial effects on hypertension, insulin sensitivity, dyslipidemia and inflammation." (PMID 30410448, 2018). "Metformin decreased glucose concentrations, reduced metabolic syndrome, as well as insulin dose requirement more than insulin therapy alone, 1 year after treatment." (PMID 29338714, 2018). "The development of a low-grade inflammatory state seen in metabolic syndrome represents another mechanism by which the gut microbiome affects insulin metabolism, described as metabolic endotoxemia." (PMID 29462993, 2018).
metabolic syndrome (continued). "Excessive weight gain in diabetic patients was associated with elevated waist circumference and blood pressure, lower insulin sensitivity, dyslipidemia, and with more extensive atherosclerosis in further observations." (PMID 30518100, 2018). "ALA and LC n-3 PUFA supplementation prevented hepatic steatosis and dyslipidemia by inhibiting lipogenesis and increasing insulin sensitivity." (PMID 30026586, 2018). "Except for fasting glucose, parameters related to metabolic syndrome, such as weight, BMI, waist circumference, fasting insulin, TGs, and blood pressure, were significantly higher in subjects with the TE type." (PMID 29853979, 2018). "Rates and intensity of metabolic dysfunction are higher in subjects with monophasic curves, who have lower insulin sensitivity and beta-cell function and a higher prevalence of prediabetes and metabolic syndrome." (PMID 30115058, 2018). "Metabolic syndrome was more decreased in the metformin-insulin group than in the insulin alone group after treatment (−8.9 ± 1.3 vs. 2.5 ± 0.6%, p = 0.028)." (PMID 29338714, 2018). "Metabolic syndrome prevalence was significantly decreased in the metformin-insulin group compared with the insulin alone group after treatment (−8.9 ± 1.3 vs. 2.5 ± 0.6%, p = 0.028)." (PMID 29338714, 2018). "At the population level, plasma insulin levels are distributed between two poles of hypo (Type I and II diabetes mellitus) and hyper (insulin resistance and the Metabolic Syndrome, MS) insulinemia." (PMID 29430572, 2017). "According to the results, the pigs presented several features, including normal fasting glycemia, hyperinsulinemia and dyslipidemia, similar to insulin-resistant or IGT prediabetic subjects." (PMID 29046729, 2017). "The components of metabolic syndrome, such as disturbed glucose and insulin metabolism (high glucose level), overweight and abdominal fat distribution, dyslipidemia, and hypertension are one of the major consequences of CVDs and CVDs-related mortality." (PMID 28878680, 2017). "Conversely, evidence suggested that increased acetate levels in HFD microbiota relay into the parasympathetic nervous system activation driving ghrelin secretion and glucose-stimulated insulin secretion, leading to hyperphagia and metabolic syndrome." (PMID 29056925, 2017). "Fasting biochemical evaluation and liver imaging revealed persisting metabolic dyslipidemia, fatty liver, raised plasma testosterone and insulin, and relatively normal adiponectin and leptin." (PMID 29242557, 2017). "Although the previously reported prevalence of metabolic syndrome was rather low at 3% in our adolescents, our findings on insulin resistance are of public health concern." (PMID 28617856, 2017). "L-C appears to be particularly suitable as a treatment for metabolic syndrome patients, who are often obese, insulin resistant, and hypertensive." (PMID 28497060, 2017). "Pro-inflammatory cytokines can increase IL-6 production, reduce adiponectin secretion, and influence insulin sensitivity, and these factors all create conditions suited to the development of metabolic syndrome." (PMID 28840832, 2017). "The age-specific variation in the prevalence of dyslipidemia is believed to be due to age-related decline in sensitivity of peripheral tissues to insulin and increase in metabolic disorders of carbohydrates and lipids." (PMID 28376848, 2017). "Several lines of evidence suggest that hyperinsulinemia contributes significantly to the fatty liver and dyslipidemia seen in common insulin-resistant states." (PMID 28541532, 2017). "The model-based validation performed in the present study supports the utilization of low-cost, insulin-based indexes for the assessment of glucose tolerance in Zucker rat, reliable animal model of human metabolic syndrome." (PMID 28264067, 2017).
metabolic syndrome (continued). "Offspring born to fathers that underwent this intense exercise program were heavier, had increased fat accumulation, were glucose intolerant, and had higher fasting insulin levels, indicating metabolic syndrome." (PMID 28208792, 2017). "DI rapidly impaired glucose metabolism and lipid profile, inducing a decrease in insulin sensitivity and dyslipidemia." (PMID 29081752, 2017). "Prenatal androgenization produces features of the metabolic syndrome in rodents, including increased body weight and visceral adiposity, impaired insulin secretion, and hepatic triglyceride content." (PMID 28465822, 2017). "RS is known to exert important physiological effects that go beyond resistance to digestion, including modulation of satiety perception, dyslipidemia, insulin sensitivity, and glycemic control in healthy, obese subjects and in patients with metabolic syndrome." (PMID 28677623, 2017). "Theoretically, interrupting the vicious cycle by decreasing the insulin level or activating lipophagy exhibits the benefits to alleviate the ER stress, improve insulin sensitivity and resolve metabolic syndrome-related abnormalities." (PMID 28831172, 2017). "Blunted insulin sensitivity substantially contributes to many metabolic disorders, including central obesity, hypertension, hyperglycaemia, dyslipidemia and atherosclerotic vascular disease." (PMID 28912840, 2017). "The purpose of the study was to determine the influence of a short-term elevation in dietary protein on hepatic and peripheral insulin sensitivity in twelve older subjects (51–70 yrs) with metabolic syndrome." (PMID 28713581, 2017). "The mice were resistant to diet- and age-induced metabolic syndrome and exhibited improved glucose tolerance and increased insulin sensitivity." (PMID 28744254, 2017). "Insulin sensitivity was assessed by estimated glucose disposal rate (eGDR), and metabolic syndrome (MS) was defined by the World Health Organization criteria." (PMID 28225861, 2017). "Kidney disease and metabolic syndrome in Zucker rats acts synergistically on glucose homeostasis and reduced insulin sensitivity." (PMID 28459862, 2017). "Common features of an insulin resistant state and AD include inflammation, dyslipidemia, amyloidogenesis and overt bioenergetic dysfunction." (PMID 29163128, 2017). "The authors also observed significant correlation with clinical indices of metabolic syndrome such as waist circumference, body fat percentage, fasting plasma insulin, total and LDL cholesterol." (PMID 27988894, 2017). "These reviews concluded that contemporaneous adult markers of BMI are the better predictor of current markers of triglycerides, insulin insensitivity, and metabolic syndrome." (PMID 29279776, 2017). "Other studies have also reported that an independent contribution of childhood body size in affecting blood lipid status, insulin levels, metabolic syndrome or cardiovascular disease is unlikely." (PMID 29208999, 2017). "Chemerin is an adipokine and has been shown to play an important role in the metabolic syndrome linking inflammation of adipose tissue with insulin resistance and body fat accumulation." (PMID 28759013, 2017). "With Metabolic Syndrome at epidemic levels, it is timely to examine the impact of a chronically elevated insulin milieu upon the functionality of immunocytes." (PMID 29430572, 2017). "Approximately 70% of women with PCOS have dyslipidemia, and hypertriglyceridemia is a characteristic metabolic abnormality of insulin resistant individuals." (PMID 28542421, 2017). "In both genders, mean values of IDF-metabolic syndrome components as well as fasting insulin and HOMA-IR were within normal ranges." (PMID 28683146, 2017). "MONW subjects have a normal weight but metabolic alterations typical of MetS (such as high blood pressure, low insulin sensitivity and dyslipidemia)." (PMID 27894098, 2017).